IL6 (interleukin 6)
Diseases named in the same sentence as IL6 in open-access papers (continued):
Sharing a sentence is not in itself a finding about the gene and the disease.
tumor (continued). "In summary, IL-6 serves as a critical factor involved in the immunosuppression of T cells and tumor cells mediated via the IL-6/JAK1/Stat3 signaling pathway." (PMID 35550592, 2022). "CAR-T20 increased human IFN-γ, murine TNF and murine IL-6 levels and decreased human IL-10 levels in tumor-bearing mice." (PMID 36352168, 2022). "A series of histological staining, including immunohistochemistry (IL-6, IL-10, TGF-β and Navi1.7) and TUNEL were conducted to reveal the underlying mechanism of anti-tumor effect of CB/Lid-n on a VX2-tumor bearing model." (PMID 36221084, 2022). "IL-6-mediated activation of the JAK/STAT3 signaling pathway by autocrine or paracrine means is required for malignant tumor proliferation." (PMID 36313280, 2022). "The chemokine ligand, RANTES, and IL-6 released by tumor cells promote their growth through autocrine and paracrine mechanisms, and the simultaneous expression of both results in a more aggressive phenotype." (PMID 35845981, 2022). "Subsequently, the IL-6/sIL-6R complex activated membrane-bound gp130 to increase STAT3 phosphorylation in the tumor cells." (PMID 36551971, 2022). "PMCs prevent initial tumor cell invasion by secreting TNFα, CRC cells secrete IL‐6, and IL‐10 converts these anti‐tumorigenic PMCs to a pro‐tumorigenic M2 phenotype favoring tumor progression." (PMID 35791509, 2022). "To validate the differential expression of IL-6 in seminomatous tissue with respect to the different tumour regions (TF and TC), we performed qRT-PCR." (PMID 35022523, 2022). "The Q-PCR results from all the tumors of each treatment group showed that several chemokines and cytokines were positively correlated with tumor size, including IL-4a, IL-6, IL-10, CSF-1, CSF-2, INF-r, and NOS-2." (PMID 35058524, 2022). "The mutated Fc-domain can induce activation of NK cells more potently, which mounts robust inflammatory responses including production of IFNγ, TNFα, and IL6 secreted from NK cells to further enhance immune reaction in tumor microenvironment." (PMID 36922936, 2022). "IL-6 is over-represented in the serum of CRC-affected patients, and its high level is associated with increased tumor growth and aggressiveness, and poor clinical outcome." (PMID 35625868, 2022). "Tumor-derived exosomes induce proinflammatory cytokine expression and PD-L1 regulation in M0 macrophages through IL-6/STAT3 and TLR4 signaling pathways." (PMID 36176299, 2022). "In the process of tumor development, IL-6, as a proinflammatory factor, has antiapoptosis effects, promotes cell proliferation, and blood vessel formation." (PMID 35392643, 2022). "The relative abundance of Firmicutes and the F/B ratio showed positive correlations with large tumor numbers, Ki-67-positive cells, colonic mRNA levels of Il1b and Tnfa, and serum levels of IL-1β and IL-6." (PMID 36312913, 2022). "When inhibiting synthesis of human IL‐6 from PC cells by RNA silencing and inhibition of human IL‐6/gp130 axis by tocilizumab, anti‐IL‐6R antibody, the growth of tumor was suppressed in the N‐inv model." (PMID 35578571, 2022). "Gene expression also differed in the same tumor, with IL6 and NLRP6 being low expressed in kidney chromophobe (KICH) while GSDMC was high." (PMID 35795676, 2022). "IL-6 expression is elevated in tumor cell lines that induce MDSCs and in plasma of cancer patients, where its concentration positively correlates with the level of circulating MDSCs." (PMID 35444651, 2022). "Here, TLRs have been reported to enhance immunotolerance through their regulated expression of IL-1β and IL-6 in tumor and stromal cells." (PMID 34918208, 2022).
tumor (continued). "TAMs present in the omentum predominantly have an anti-inflammatory phenotype to facilitate tumor progression by secreting cytokines such as IL-6 and IL-8." (PMID 36142615, 2022). "To ascertain the role of RasGRP1, we used lentivirus to overexpress RasGRP1 in Huh 7 cells and found that RasGRP1 overexpression significantly inhibited the tumour-promoting effect of IL-6." (PMID 36385095, 2022). "In this regard, systemic thermal therapy has been shown to be associated with IL-6 production, leading to ICAM-1 expression by the tumor blood vessels and, thus, favoring the entry of T cells into the tumor site." (PMID 35681548, 2022). "In the tumor microenvironment, monocytes respond to paracrine stimuli from cancer cells by secreting soluble mediators, most notably IL-6, and these participate in tumor growth, invasion, intravasation, and metastasis." (PMID 35155394, 2022). "Most neoplastic cells and tumor-associated cells in the TME secrete factors that block the activation of NK cells, such as IL-6, IL-10, IDO, TGF-β, and prostaglandin E2 (PGE2), through downregulating NK cells activating receptors including NKG2D." (PMID 36072957, 2022). "Cells such as microglia and tumor-associated macrophages secrete cytokines, including TNF-α and IL-6, within the tumor microenvironment to further modulate NF-κB signaling." (PMID 35922651, 2022). "For example, CSC-derived IL-10 and IL-6 were demonstrated to potentiate a pro-tumor phenotype of GAM." (PMID 36570441, 2022). "Stratification and multivariate analyses further revealed that the baseline level of IL-6 in plasma and tumor tissues was an independent prognostic predictor." (PMID 35550592, 2022). "IL-6 is a pleiotropic protein promoting several processes involved in tumor initiation and progression, e.g., proliferation, survival, and invasion of tumor cells." (PMID 36230528, 2022). "SCFAs can reduce the down-regulation of macrophage pro-inflammatory mediators such as IL-6, thereby inhibiting tumor growth." (PMID 35309293, 2022). "It has also been suggested that IL-6, IL-22, and IL-10 can influence tumor drug resistance by regulating apoptosis-related proteins like BCL-2 and IAPs." (PMID 36245983, 2022). "Activation of MERTKR in TAM promotes tumor progression by inducing the expression of the proinflammatory cytokines, IL-1β, IL-6, and TNF." (PMID 36679900, 2022). "DCs also promote anti-tumor immunity by secreting proinflammatory cytokines, including IL-6, TNFα, and type I and II interferons (IFNs)." (PMID 36248881, 2022). "Studies have reported that the tumor cells with constitutive expression of STAT-3 maintain the activity of this pathway through positive autocrine feedback between IL-6 and the IL6R." (PMID 35465350, 2022). "IL-6 secreted by CAFs promotes cancer stemness, chemoresistance, and invasion through Nanog activation and eventually promotes tumor growth and metastasis." (PMID 35740372, 2022). "Double staining for PU.1 and IL-6 confirmed that many PU.1+/IL-6+ cells are present in the mucosa of the tumour-bearing wild-type mice." (PMID 35793807, 2022). "Specifically, several cytokines and growth factors released by immune cells and tumor cells, such as IL-1β, IL-6, and TGF-β promote the development of MDSCs." (PMID 35656301, 2022). "Neutralizing IL-6 or blocking IL-6 receptors would inhibit IL-6/IL-6 receptor axis, abrogate the protection of tumor cells from spontaneous- and drug-induced apoptosis, and improve the cellular sensitivity to chemotherapy agents." (PMID 36104733, 2022). "In this review, we aimed to summarise the effects of IL-6 on both stromal and parenchymal cells, particularly on promoting tumour invasiveness and thus ensuing metastasis." (PMID 36429126, 2022). "Pro-inflammatory mediators such as IL-22, IL-6, IL-2, and IL-17 play a key part in maintaining tumor microenvironment, promoting immunosuppression, angiogenesis, and coordinating the interactions between immune cells." (PMID 36249057, 2022).
tumor (continued). "Since chronic inflammation can promote tumor progression, high expression of IL-6 can also be present in TME." (PMID 36291659, 2022). "We found that in adjacent non-tumor breast tissues, both AnxA1 and IL-6 were expressed in glandular and in the myoepithelial cell layer." (PMID 35626741, 2022). "IL6, a main inflammatory cytokine, participates in the poor tumor microenvironment, promoting tumorigenesis and cancer development." (PMID 35102195, 2022). "MSCs have been shown to release factors such as VEGF, FGF-2, PDGF, HGF, BDNF, SDF-1α, IGF-1, IGF-2, TGF-β, TNFα IGFBP-2, LIF, M-CSF, MIP-2, IL-8, IL-6, and IFNγ that promote tumour survival, proliferation, migration, invasion, and angiogenesis." (PMID 35954425, 2022). "We examined the metastatic ability of HCC cells after IL-6 treatment and found that miR-133a-3p was sorted into exosomes after IL-6 stimulation and was subsequently released into the tumor microenvironment." (PMID 35432524, 2022). "Driven by memory B cells and a range of cytokines (including TNF, IL-2, IL-6, and IFNγ), T cells home to the tumor bed and release perforin and granzyme or Fas/FasL pathways to destroy tumor cells." (PMID 36704336, 2022). "Pleural and tumor levels of MPE-related proinflammatory mediators (IL-6; VEGF; monocyte chemoattractant protein-1, MCP-1; TNFA; secreted phosphoprotein 1, OPN; and macrophage inflammatory protein 2, MIP2) were not affected by macrophage CSF1R ablation." (PMID 35315360, 2022). "On the other hand, as an endogenous pyrogen, TNF-α is able to mediate fever, apoptotic cell death, sepsis (through IL-1 and IL-6 production), cachexia, tumor regression, as well as carbohydrate metabolism and adipogenesis inhibition." (PMID 35406450, 2022). "Mast cells produce many different mediators (vascular endothelial growth factor (VEGF), tumour necrosis factor, interleukin-6, tryptase, histamine etc.)that can modify the tumour microenvironment, for example by promoting vascular development." (PMID 35761297, 2022). "Chronic inflammation can cause DNA damage and proinflammatory cytokines, including TNF, IL-1, and IL-6, and can augment tumor growth and metastasis." (PMID 36450739, 2022). "The soluble factors derived from adipocytes, called adipokines, including adiponectin, leptin, IL-6, and tumor necrosis factor α, are involved in tumor progression." (PMID 35805003, 2022). "Many tumor cells can also produce PTHrP, IL-1, IL-6, PGE2, TNF, CSF-1, and other factors not only to promote their own survival, but also to increase the production of osteoclasts at the same time." (PMID 36230816, 2022). "It is associated with the release of different cytokines, including, among others, IL-6 and tumor necrosis factor, which can potentially favor tumor progression." (PMID 35888601, 2022). "Tumor-infiltrating M1-type macrophages (anti-tumorigenesis) secrete proinflammatory cytokines (e.g., IL-1β and TNF-α), whereas tumor-infiltrating M2-type macrophages (pro-tumorigenesis) secrete anti-inflammatory cytokines (e.g., IL-6 and IL-10)." (PMID 36246355, 2022). "Tumor-induced systemic inflammation promotes tumorigenesis, invasion, and metastasis via inflammatory mediators, such as tumor necrosis factor-alpha, interleukin-6, and interleukin-10." (PMID 35410196, 2022). "In these signaling pathways, STAT3 is considered to be a key signaling molecule of the IL-6-gp130 pathway because it acts as an oncogenic driver and plays an important role in mediating tumor-promoting inflammation." (PMID 36010693, 2022). "It was reported that adipocyte cells secreted leptin, TNF, IL-6, and adiponectin to induce a change in tumor gene expression related to angiogenesis signatures." (PMID 36014894, 2022). "CTCL patients had higher circulating levels of IL-6, IL-8, IL-10, TGFβ, PGE2 and MMP7 which are factors released by tumor-associated macrophages in tumor microenvironment." (PMID 36059695, 2022).
tumor (continued). "At last, the moDCs were derived from monocytes and produced pro-inflammatory cytokines, including TNF, IL-12, and IL-6, to promote tumor progression." (PMID 35585567, 2022). "After M2 polarization, inflammatory factors such as TNF-α and IL-6 are produced, which promote cancer in tumor microenvironment; this effect is more obvious in hypoxic environments." (PMID 35145526, 2022). "Recruitment of tumor-associated macrophages by the Yes-associated protein YAP, an oncogene overexpressed in a subset of HCC patients, also involves IL-6 signaling." (PMID 36276076, 2022). "A possible mechanism is as follows: cytokines such as tumor necrosis factor and interleukin 6 are produced by tumor cells or surrounding cells and promote protein degradation and decreased synthesis." (PMID 35463384, 2022). "When inflammatory substances like interferon-gamma and lipopolysaccharide excite monocytes, they activate M1 macrophages, which can emit inflammatory factors like IL-6 and tumor necrosis factor-alpha and phagocytize invading infections and tumor cells." (PMID 36589842, 2022). "In the present study, we found that MHCC-97L cells with low metastatic potential exhibited enhanced invasive and metastatic abilities by releasing exosomes containing tumor suppressor miR-133a-3p upon IL-6 treatment." (PMID 35432524, 2022). "IL-6 is one of the major cancerous media cytokines that controls the pattern of tumor proliferation, apoptosis, metabolism, progression, metastasis, and angiogenesis." (PMID 35269343, 2022). "Mature DC numbers or functions were improved leading to better immune control of the tumour in several mouse models: IL-6 KO mice; tumours treated with anti-VEGF antibody; and treatment with anti-IL-8 monoclonal antibody." (PMID 35355992, 2022). "Among them were genes associated with blood clotting (FGA, FGG) and genes associated with changes in the immune characteristics of a tumor (ENAM, IGFBP1, IL6)." (PMID 36028558, 2022). "Various cells, such as tumor-associated macrophages, fibroblasts, granulocytes, dendritic cells, lymphocytes, and CRC cells are all sources of IL-6 in the TME." (PMID 35463300, 2022). "IL-6 levels have been significantly correlated with tumor invasion, severity, spreading, and chemo-resistance depending on the cellular downstream pathways after binding to its specific receptor." (PMID 35406495, 2022). "Chronic secretion and exposure to IL-6 proinflammatory cytokine plays a significant role in tumor promoting inflammation resulting in a feedback loop of persistent activation of pro-inflammatory signaling and tumor progression." (PMID 36564457, 2022). "In the second, IL-6 was expressed in tumor stroma adjacent to regions with HER2pos/pSTAT3pos tumor cells (Pattern 2)." (PMID 35565421, 2022). "Experiments on mice showed that miR-199a inhibited tumor growth and metastasis, and promoted the expression of inflammatory factors IL-6 and IFN-α." (PMID 35844793, 2022). "The suppression of inflammatory-related cytokines (IL-6 and IL-10) can inhibit tumor cell proliferation and metastasis via immunosuppression." (PMID 35630704, 2022). "Normalized IL‐6 mRNA levels in N‐inv tumor (2.289 ± 1.048) were obviously higher than those in SC tumor (0.656 ± 0.512, p = 0.002) at day 28 after inoculation." (PMID 35578571, 2022). "Excessive production of HMGB1 causes chronic inflammatory responses, mediated by the release of cytokines such as IL-6 and IL-8 which, in turn, stimulate carcinogenesis through tumor cell proliferation, angiogenesis, EMT, invasion, and metastatization." (PMID 36012593, 2022). "Cytokines regulated by NF-κB and STAT3 can either be tumor-inducing (TNF, IL-23, IL-6) or tumor-inhibiting (IFNα, IFNγ, TRAIL)." (PMID 35327456, 2022). "Tumor macrophages of CSF1Ri-administered animals exhibited significantly lower expression of Il6 and Vegfa (in MC38 model) or Il6 and Angpt2 (in LLC model)." (PMID 35315360, 2022).
tumor (continued). "For example, IL-1β and IL-6 are pro-inflammatory cytokines that can promote the activation of CAFs through NF-κB and JAK-ROCK-STAT3 signaling pathways, thus causing tumor progression." (PMID 35479936, 2022). "IL6 secreted by tumor cells interacts with gp130 and interleukin 6 receptor (IL-6R) on ALDEFLUOR-positive mesenchymal cells (MCs) and can promote the homing of MSCs to the tumor sites, as well as stimulate CXCL7 expression by these cells." (PMID 35251985, 2022). "Fourteen days of ACD7507 treatment significantly decreased pro-tumor cytokines IL-6 and IL-10 in tumor samples." (PMID 36077755, 2022). "Cytokines produced by tumor and surrounding cells such as GM-CSF, G-CSF, and IL-6 stimulate granulopoiesis in the bone marrow and recruit neutrophils to the tumor site." (PMID 36031601, 2022). "M2-like TAMs secrete a variety of chemokines and interleukins including CCL2, IL-6 and IL-10, to enhance tumor cell proliferation." (PMID 35672862, 2022). "Curcumin remarkably inhibits the expression of arginase-1 (Arg-1) and ROS of MDSC in tumor tissues, and also decreases IL-6 in serum and tumor tissues of LLC-bearing mice to prevent the multiplication of MDSC." (PMID 36439106, 2022). "In previous studies, higher IL-6 levels were found to be important for TNBC tumor growth and metastases, and serum IL-6 levels increased with pathological grades." (PMID 35626741, 2022). "The IL-6-adenosine positive feedback loop between CD73+ γδTregs and cancer-associated fibroblast (CAF) was also involved in tumor progression in breast cancer patients." (PMID 35747139, 2022). "IL-6-producing tumors were shown to be more resistant to NK cell cytotoxicity, suggesting the importance of IL-6 signaling in determining tumor cell sensitivity." (PMID 36230984, 2022). "ADT is also known to generate stress on tumor‐surrounding milieu by increasing tissue hypoxia or production of many secretory factors, such as cytokines (IL‐6, IL‐8), known to induce NED of PCa,39 in parallel with genetic alteration." (PMID 35184376, 2022). "Low CXI was significantly associated with a more advanced tumor–node–metastasis (TNM) stage, a higher level of serum C-reactive protein, serum interleukin-6, and NLR, but also a decreased level of serum prealbumin and albumin." (PMID 36139560, 2022). "The mtDNA reduced the secretion of cytokines such as IL-6, decreasing the body’s anti-tumor immune capacity and promoting the progress of the tumor." (PMID 35454769, 2022). "Many studies reported the secretion of IL-6 from CAFs52,53 and its various tumor promoting downstream effects." (PMID 36180493, 2022). "Inflammation also produces growth factors, cytokines like interleukins (IL-6), and a protein complex like NF-kB that can give tumour progenitors a stem cell-like phenotype or stimulate stem cell expansion." (PMID 36555218, 2022). "IL-6–induced activation of the ROBO3/STAT3 pathway in CLA-like tumor cells resulted in the induction of BL-characteristic gene signatures and the acquisition of an EMT-like phenotype." (PMID 35993361, 2022). "This suggests that systemically secreted IL-6 from the tumor is necessary to sustain the type 3 Th immune response outside the tumor." (PMID 36142210, 2022). "And then, GBM tumor cell-induced IL-6 activates STAT3 in astrocytes, which subsequently drives IL-6 to stimulate GBM tumor cells and further promotes STAT3 signals and enhances downstream events." (PMID 35572545, 2022). "Chimeric monoclonal antibody siltuximab that binds IL6 is currently investigated for the treatment of several tumor types including prostate cancer and metastatic renal cell cancer." (PMID 36253762, 2022). "In resistant HCC cells, enhanced autocrine generation of growth factors, such as interleukin (IL)-1, IL-4, IL-6, and IL-8, was observed in comparison to tumor cells responsive to treatment." (PMID 35203283, 2022). "In NPC, IL6 activates JAK2/STAT3 signaling pathway to promote tumor progression, thus affecting the prognosis of patients." (PMID 36506508, 2022).